MBD6 (methyl-CpG binding domain protein 6)
Description:
Non-catalytic component of the polycomb repressive deubiquitinase (PR-DUB) complex, a complex that specifically mediates deubiquitination of histone H2A monoubiquitinated at 'Lys-120' (H2AK119ub1). Important for stability of PR-DUB components and stimulating its ubiquitinase activity. As part of the PR-DUB complex, associates with chromatin enriched in histone marks H3K4me1, H3K4me3, and H3K27Ac, but not in H3K27me3. MBD5 and MBD6 containing complexes associate with distinct chromatin regions enriched in genes involved in different pathways. Heterochromatin recruitment is not mediated by DNA methylation. The PR-DUB complex is an epigenetic regulator of gene expression, including genes involved in development, cell communication, signaling, cell proliferation and cell viability; may promote cancer cell growth.
Synonyms: KIAA1887
Tractability: No criterion of Open Targets' tractability assessment is met for any kind of drug.
Gene: Protein-coding gene on chromosome 12 (57,520,710 to 57,530,148, forward strand). Ensembl gene ENSG00000166987.
Subcellular location: Nucleus; Chromosome
Subcellular location (Human Protein Atlas): Nucleoplasm
Pathways (Reactome):
Metabolism of proteins: UCH proteinases
Gene Ontology:
Molecular function: chromatin binding; DNA binding; protein binding
Cellular component: chromocenter; chromosome; nucleoplasm; nucleus
Genetic constraint (gnomAD): Loss-of-function variants: 22 observed, 62.86 expected, observed/expected ratio (o/e) 0.35, 90% interval 0.25 to 0.5. The upper end of that interval is the gene's LOEUF score, 0.5, which puts it in group 2 of 6, group 1 being the genes least tolerant of losing a copy. Missense variants: 1,316 observed, 1,280.2 expected, observed/expected ratio (o/e) 1.03, 90% interval 0.98 to 1.08. Synonymous variants: 536 observed, 532.17 expected, observed/expected ratio (o/e) 1.01, 90% interval 0.94 to 1.08.
Homologues: Orthologues: chimpanzee MBD6 (99% identical), macaque MBD6 (99% identical), pig MBD6 (96% identical), rabbit MBD6 (95% identical), dog MBD6 (94% identical), mouse Mbd6 (93% identical), rat Mbd6 (93% identical), guinea pig MBD6 (87% identical), tropical clawed frog mbd6 (36% identical), zebrafish mbd6 (26% identical), Drosophila melanogaster sba (16% identical). Paralogues in human: MBD5 (27% identical).
Diseases named in the same sentence as MBD6 in open-access papers:
MBD6 is named in the same sentence as 13 diseases in open-access papers, as found by Europe PMC text mining. Sharing a sentence is not in itself a finding about the gene and the disease. The quoted sentences say what the papers report.
leukaemia (2 papers, 2024 to 2025). "TET2-mutant human leukaemia becomes dependent on this gene activation pathway, with MBD6 depletion selectively blocking proliferation of TET2-mutant leukaemic cells and largely reversing the haematopoiesis defects caused by Tet2 loss in mouse models." (PMID 39358506, 2024). "In the most recently published research article in Nature, it has been demonstrated for the first time that the TET2 regulates the chromatin structure and leukaemogenesis in stem cells and leukaemia cells via MBD6 (binds 5-methycytosine residues in RNA) and NSUN2 (a RNA methylase)." (PMID 39757230, 2025).
autism (1 paper, 2023). Persistent deficits in social interaction and communication and interaction as well as a markedly restricted repertoire of activity and interest as well as repetitive patterns of behavior. "Individual 12 (F11-II-2) also harbors a de novo frameshift VUS in MBD6 (MIM: 619458, c.2337dup [GenBank: NM_052897.4] [p.Gly780Trpfs∗13]); this gene is suspected to be associated with autism and language delay and could contribute to her phenotype." (PMID 37071997, 2023).
lung carcinoma (1 paper, 2022). "Consistently, genome-wide CRISPR screenings by DepMap across different lung cancer types revealed that lung cancer cells are generally more sensitive to MBD6 depletion, while MBD5 is not essential for lung cancer cell viability." (PMID 36180891, 2022).
mental retardation (1 paper, 2010). "It is unknown whether MBD5 or MBD6 also bind methylated DNA; this question has interest for basic research, but also practical consequences for human health, as MBD5 deletions are the likely cause of certain cases of mental retardation." (PMID 20700456, 2010).
Obesity (1 paper, 2022). Accumulation of substantial excess body fat. "However, there were some differences in DCM from obesity—MBD6, CREB5, and PDE3B were down-regulated and the others were up-regulated." (PMID 36547458, 2022).
Sepsis (1 paper, 2020). Sepsis is defined as life-threatening organ dysfunction caused by a dysregulated host response to infection. "Gene entities shared between sepsis and severe sepsis response hubs are; TDRD9 – LIN7A, GPR84 – ENTPD7, PYCT1A and ZDHHC19, CD177 – DDAH2 and RGL4, SLC16A3 – DENND3 and MBD6, MYL9 – CMTM5, ITGB3, ITGA2B, NRGN, SELP and TREML1." (PMID 32318053, 2020).
Wilson disease (1 paper, 2017). A very rare inherited multisystemic disease presenting non-specific neurological, hepatic, psychiatric or osseo-muscular manifestations due to excessive copper deposition in the body. "Our findings imply that reduced stability and enhanced dynamics of MBD1 or MBD6 is the origin of ATP7B dysfunction in Wilson disease patients with the G85V or G591D mutation." (PMID 27744583, 2017). "In summary, introducing a larger amino acid (Asp or Val instead of Gly) at position 386 in MBD4 (as found in MBD1 and MBD6 in Wilson disease patients) results in enhanced domain structural dynamics in silico and decreased resistance towards thermal perturbations in vitro." (PMID 27744583, 2017).
tumor (5 papers, 2022 to 2025). "Consequently, loss of MBD6 significantly reduces SCLC tumor growth in vitro and in vivo, and therefore, our study may provide potential targets for SCLC clinical therapies." (PMID 36180891, 2022). "As a result, we found that depletion of MBD6 significantly repressed tumor growth in animals, and significantly delayed progression of disease." (PMID 36180891, 2022). "Finally, to determine the impact of MBD6 on SCLC tumor growth in vivo, we injected NCI-H510 human SCLC cell lines transduced with either non-targeting CRISPR-Cas9 or two distinct MBD6 sgRNAs into the right flank of nude mice." (PMID 36180891, 2022). "Therefore, depletion of MBD6 leads to a global loss of BAP1 occupancy at the chromatin, resulting in a reduction of BAP1-dependent gene expression and tumor growth in vitro and in vivo." (PMID 36180891, 2022). "Furthermore, the reduced levels of L-lactic acid slow tumour progression through histone H4K16 lactylation and regulate the expression of the BEST1, GRAMD4, and MBD6 genes, with this mitochondrial effector serving as an apoptotic signal induced by E2F1." (PMID 41249152, 2025). "In addition, the MBD5 and MBD6 subunits are critical for maintaining the stability of the BAP1 complex and therefore are essential for BAP1-dependent tumor cell growth in vitro and in vivo." (PMID 36180891, 2022).
cancer (2 papers, 2022 to 2025). A tumor composed of atypical neoplastic, often pleomorphic cells that invade other tissues. "Mutations within MBD5 and MBD6 have been detected in multiple human cancers, as well as neuronal disorders." (PMID 36180891, 2022). "We characterize MBD5 and MBD6 as important regulators of the BAP1 complex and maintain its transcriptional landscape, shedding light on the therapeutic potential of targeting MBD5 and MBD6 in BAP1-dependent human cancers." (PMID 36180891, 2022). "In BAP1-dependent human cancers, such as small cell lung cancer (SCLC), MBD6 tends to be a part of the predominant complex formed." (PMID 36180891, 2022). "MBD6, as a non-catalytic component of the polycomb repressive deubiquitinating enzyme complex, participates in the epigenetic regulation of gene expression, influencing cell proliferation and survival and promoting cancer cell growth." (PMID 41249152, 2025). "Additionally, MBD6, a non-catalytic component of the polycomb repressive deubiquitinating enzyme complex, inhibited cancer cell growth by regulating cell proliferation and survival." (PMID 41249152, 2025).
hematological malignancies (1 paper, 2025). "MBD6 promoted a more open chromatin state and increased transcription in stem cells in malignancies with TET2 depletion, suggesting a potential therapeutic avenue for targeting TET2‐mutant hematological malignancies via the development of MBD6 inhibitors." (PMID 40116537, 2025).
MBD6 also shares sentences with these, for which no sentence is quoted: acute myeloid leukaemia (1 paper); language delay (1); Rett syndrome (1).